MALAT1 (metastasis associated lung adenocarcinoma transcript 1)
Diseases named in the same sentence as MALAT1 in open-access papers (continued):
Sharing a sentence is not in itself a finding about the gene and the disease.
prostate carcinoma (continued). "In prostate cancer, MALAT1 leads to tumorogenesis by inducing tumoral cell proliferation." (PMID 36163080, 2022). "It has been reported that STAT3 may bind to the MALAT1 promoter and transcriptionally stimulate its expression in a model of prostate cancer identifying the IL-8/STAT3/MALAT1 axis as a key regulator during prostate tumorigenesis." (PMID 35814429, 2022). "Assessment of MALAT1 Knockout on prostate cancer cells migration." (PMID 36163080, 2022). "Recent studies in prostatic cancer cells determined that MALAT1 promotes the proliferation, migration, and invasion of tumour cells by acting as a miR-145 sponge, suppressing its anti-tumoral activity, and the downregulation of MALAT1 increases miR-145 and decreases cell migration and invasion." (PMID 35052757, 2021). "Our results suggest that the regulatory pathway of MALAT1 SNPs in prostate cancer might be different from other malignancies." (PMID 34574033, 2021). "The presence of MALAT1 SNPs rs619586 and rs1194338 seems to enhance oncogenesis in prostate cancer." (PMID 34574033, 2021). "Metastasis-associated lung adenocarcinoma transcript 1 (MALAT-1), the first identified cancer-associated lncRNA, is upregulated in malignancies such as ovarian, lung, colon, cervical, and prostate cancer and employed as a prognostic factor for metastasis and survival." (PMID 32854207, 2020). "It is reported that lncRNA MALAT1 binds to EZH2 in castration-resistant prostate cancer." (PMID 31830649, 2020). "In prostate cancer, lncRNA MALAT-1 can be used to distinguish patients from healthy controls." (PMID 32992718, 2020). "For example, the lncRNA MALAT1 is overexpressed with high risk HPVs infection while the lncRNA MALAT1/miR-145-5p/AKAP12 axis has been verified in prostate cancer." (PMID 32849815, 2020). "In addition, targeting the Malat1 and AR-v7 axis using Malat1-short interfering RNAs (siRNAs) in enzalutamide-resistant prostate cancer cell lines and mouse models suppressed enzalutamide-resistant prostate cancer progression." (PMID 32503170, 2020). "This study highlighted a novel role for MALAT1 as a controller of prostate cancer metabolism." (PMID 33375130, 2020). "MALAT1 was up-regulated in human prostate cancer tissues and cell line." (PMID 31760932, 2019). "Metastasis associated lung adenocarcinoma transcript 1 (MALAT 1), a lncRNA initially investigated in lung cancer, is also expressed in prostate cancer tissues and cell lines, with the expression level associated with high Gleason score, PSA score, and tumor size reflective of a poor risk subgroup." (PMID 30200254, 2018). "MALAT1 acts as oncogenic lncRNA in a wide variety of solid and hematological malignancies, including osteosarcoma, renal cell carcinoma, colorectal, prostate cancer, esophageal carcinoma, T, NK and mantle cell lymphomas." (PMID 29290968, 2017). "In chemotherapy-resistant prostate cancer, MALAT1 was shown to directly interact with EZH2 protein, suggesting that MALAT1 may play a key role as an RNA cofactor of EZH2 and that the EZH2-MALAT1 association may be a new therapeutic target." (PMID 28412742, 2017). "Indeed, previous studies have shown that MALAT-1 was significantly up-regulated in several types of cancers, including lung, liver, pancreatic, and prostate cancers." (PMID 27227769, 2016). "Our finding represents a proof of principle of a putative “response” upon MALAT1 silencing of two well characterized hormone-dependent genes relevant for prostate cancer, disclosing potential perspective manipulations in terms of transcription regulation of prognostic genes." (PMID 27922078, 2016). "Further clarification of the mechanisms by which Sost/Wnt/MALAT1 pathway regulate prostate cancer metastasis may open up new avenues of therapeutic intervention in treating prostate cancer metastasis to bone." (PMID 27600237, 2015).
prostate carcinoma (continued). "To test whether Sost is a regulator of MALAT1 in prostate cancer we cultured PC3 cells with recombinant human SOST for 48 h and quantified MALAT1 expression using qPCR." (PMID 27600237, 2015). "Our results suggest that reduced Sost expression in the tumor microenvironment may promote bone metastasis by up-regulating MALAT1 in prostate cancer." (PMID 27600237, 2015). "Here, we found MALAT1’s expression to be regulated by Sost, suggesting that altered Sost expression in bone microenvironment may regulate prostate cancer proliferation, migration, or invasion at least in part by modulating MALAT1 expression in prostate cancer." (PMID 27600237, 2015). "In addition, in prostate cancer patients, fragments from different regions of MALAT1 transcript were detected in plasma at higher copy number than in non-prostate cancer patients." (PMID 26516918, 2015). "Both EZH2 and MALAT1 are highly expressed in human prostate cancers, especially metastatic CRPC." (PMID 26516927, 2015). "Moreover, our previous work showed that miR-423-5p could control prostate cancer growth and invasiveness by interacting with a known cancer-related non-coding RNA, MALAT-1, which altered cell metabolism and progression." (PMID 41029313, 2025). "Concomitantly, a marked increase in the phosphorylation of H2AX foci was also noticed in MALAT1-silenced DU145 and PC3 cells, indicating the crucial role of MALAT1 in modulating the expression of several HR genes as well as genome integrity in both HR-proficient and -deficient prostate cancer cells." (PMID 37812088, 2023). "In prostate cancer, lncRNAs likewise have diagnostic (e.g., prostate cancer antigen 3, PCA3), prognostic (e.g., second chromosome locus associated with prostate-1, SChLAP1), and predictive (e.g., metastasis-associated lung adenocarcinoma transcript-1, MALAT-1) functions." (PMID 28241429, 2017). "Metastasis-associated lung adenocarcinoma transcript-1 (MALAT1) lncRNA was originally identified as a prognostic factor of tumor development and metastasis in various types of human tumors such as glioma, lung, pancreatic and prostate cancer as well as esophageal squamous cell carcinoma." (PMID 26516927, 2015). "Several lncRNAs have been used as diagnostic and prognostic markers, including the following: MALAT-1 for liver, lung, breast, and prostate cancer; HOTAIR for breast, brain, and colon cancer; OOC1 for colon cancer; and PCA3, PCAT-1, and SChLAP1 for prostate cancer." (PMID 26160837, 2015). "Liposomal loaded dexamethasone; doxorubicin and Turmeric can be considered as promising therapeutic agents for prostate cancer via modulating CRISPR/Cas9 gene editing and long non coding gene MALAT1." (PMID 38723038, 2024). "In conclusion, their work emphasizes the significance of MALAT-1 as a controller of CHKA expression and its function in the metabolic rewiring of prostate cancer cells." (PMID 38511067, 2024). "MALAT1-MVP and MALAT1-NCBP3: In a prostate cancer mouse model, MALAT1 fusions, including MALAT1-MVP and MALAT1-NCBP3, were found to be implicated in resistance to second-generation antiandrogen cancer drugs." (PMID 38919532, 2024). "A number of well-known oncogenic lncRNAs in other cancers such as DANCR, MALAT1, CCAT1, PVT1, TUG1 and NEAT1 have also been shown to act as oncogenes in prostate cancer." (PMID 37025585, 2023). "Given the increased expression of MALAT1 in prostate cancer cells, MALAT1 knockout by CRISPR/Cas9 demonstrated that Px459-MALAT1-sgRNA1 and pX459-MALAT1-sgRNA2 vectors inhibited the development and proliferation of prostate cancer DU-145 cells." (PMID 36163080, 2022). "Quercetin inhibited cell proliferation, invasion, and migration but facilitated apoptosis in prostate cancer cells via blocking the EMT process and the PI3K/Akt signaling cascade by targeting MALAT1." (PMID 35656022, 2022).
prostate carcinoma (continued). "There is a positive correlation between lncRNA MALAT1 and EZH2 expression in human castration-resistant prostate cancer tissues, in which the knockdown of lncRNA MALAT1 impairs EZH2 recruitment and upregulates expression of EZH2-repressed genes." (PMID 31830649, 2020). "For instance, MALAT1 was reported to bind EZH2 and further enhance histone 3 lysine 27 trimethylation (H3K27me3) levels at the target gene loci of EZH2 in prostate cancer cell lines." (PMID 32972446, 2020). "We found that lncRNA MALAT1 also acted as miRNA sponge to weaken the inhibition of GPR19 expression, they were bound by miR-30d, and the miRNA was a prostate cancer-related miRNA." (PMID 27528026, 2016). "However, it remains unknown whether MALAT1 affects normal mRNA splicing in prostate cancer." (PMID 26110379, 2015). "Treatment with recombinant SOST resulted in ~5.6-fold reduction in MALAT1 expression, suggesting that Sost in the tumor microenvironment may have an inhibitory effect on MALAT1 and down-regulation of Sost in the bone microenvironment may enhance MALAT1 expression in prostate cancer." (PMID 27600237, 2015). "To date, a variety of transcriptional substances in urinary exosomes have been found to play a role in prostate cancer and are potentially attractive in terms of prostate cancer biomarkers, e.g., PCA3, MALAT1, HOTAIR, miR-1290, and miR-375 are some of the more common markers." (PMID 39090720, 2024). "Collectively, these findings provide irrevocable evidence that a double-negative feedback loop between MALAT1 and miR-421 modulates the expression of HR genes in prostate cancer." (PMID 37812088, 2023). "Notably, a strong positive correlation (ρ ≥ 0.35) between MALAT1 expression and the DDR gene signature (retrieved from mSigDB) was also observed in these prostate cancer datasets." (PMID 37812088, 2023). "Linet al. showed that thedownregulated or absent expression of MALAT1 is typical mostly of normaltissue, while MALAT1 overexpression is characteristic of breast, pancreatic,liver, lung, colorectal, and prostate cancers." (PMID 37538803, 2023). "In addition, numerous lncRNAs have been reported to regulate the sensitivity of cancer cells to the cytotoxicity of tumor-reactive T cells, such as SNHG4 or MALAT1 in diffuse large B cell lymphoma, and KCNQ1OT1 in prostate cancer." (PMID 36482354, 2022). "For example, co-culture of prostate cancer PC3 cells and osteoblasts may up regulate the expression of MALAT1 in PC3 cells, and co-culture with SOSTKO osteoblasts may further enhance MALAT1 expression, promoting bone metastasis." (PMID 36452326, 2022). "In addition, several studies showed that the interaction of MALAT1 with EZH2 is involved in other cancer types, such as prostate cancer, gastric cancer, and lymphoma." (PMID 30781877, 2019). "Plasma levels of MALAT1-derived fragments are significantly elevated in patients with prostate cancer compared with those without prostate cancer." (PMID 28701723, 2017). "Also, similar results were obtained after characterizing lncRNAs MALAT1 and PCA3 as biomarkers in prostate cancer patients." (PMID 28634418, 2017). "Analysis of these lncRNAs by ChIP-Seq in prostate cancer cells showed that the eNOS-peaks were present on the HOTAIR and ANRIL promoter region before and after stimulation with 17β-estradiol (E2) and on the MALAT1 promoter region exclusively upon E2 treatment." (PMID 27922078, 2016). "Of translational relevance, we showed evidence of a potential repressive function of MALAT1 on the basal transcription of sex steroid hormone receptors target genes such as pS2 and PSA in primary prostate cancer cells and ex vivo organotypic slice cultures derived from PCa patients." (PMID 27922078, 2016).
prostate carcinoma (continued). "Four genes in particular, MALAT1, CLCN5, MLL3, and SLC25A36, that were up-regulated in metastatic prostate cancer compared to primary prostate cancer were also displayed an enhanced expression in PC3-WT osteoblast co-cultures and PC3-SostKO osteoblast co-cultures compared to PC3 alone." (PMID 27600237, 2015). "Many lncRNAs have been mapped at cancer risk loci in the human genome, such as PTCSC3 (14q13.3) in thyroid cancer, PCA3 (9q21–22) in prostate cancer, ANRIL (9p21) in prostate and breast cancers, leukemia and melanoma, MALAT1 (11q13) in liver, colorectal, prostate, bladder and lung cancers." (PMID 25338714, 2015). "After the original discovery that MALAT1 is overexpressed in NSCLC, several other studies have been published showing the overexpression of MALAT1 in a multitude of cancer types such as colorectal, breast, pancreas, bladder, and prostate cancers." (PMID 25101115, 2014). "MALAT1, a long non-coding RNA often expressed and thought to deregulate RNA splicing in CRPC patients, was shown to be a regulator of androgen receptor expression, to mediate cancer cell growth, invasion and migration and to correlate with PSA values and Gleason grading in prostate cancer." (PMID 35159020, 2022). "Previous findings have also indicated that MALAT1 induces epithelial-mesenchymal transition in breast, cervical, colorectal, esophageal, and prostate cancer cells as well as in non-transformed cell lines, namely ARPE-19 cells, HK-2 cells, and lens epithelial cells." (PMID 36458289, 2022). "Increased expression of MALAT1 was first observed in metastatic non-small cell lung cancer, followed by endometrial stromal sarcoma of the uterus, and more recently in six other types of cancer, including HCC, breast, pancreas, lung, colon, and prostate cancers." (PMID 23862139, 2013). "Up-regulation of MALAT1 in metastatic prostate cancer and PC3 cells co-cultured with SostKO osteoblasts suggests that reduced Sost expression in the bone microenvironment may promote prostate cancer metastasis at least in part through the up-regulation of non-coding RNA MALAT1." (PMID 27600237, 2015). "In a novel development, the PCA3 prostate cancer gene, PCAT-1, MALAT-1 PCGEM, and several other long non-coding RNAs were investigated for potential deregulation in PC." (PMID 38723038, 2024). "Our data suggests the presence of a double-negative feedback loop between MALAT1 and PARP1 in both AR-negative and AR-positive prostate cancer cell lines." (PMID 37812088, 2023). "Similarly, our quantitative PCR (qPCR) data with multiple prostate cancer cell lines (PC3, DU145, LNCaP, 22RV1, and VCaP) also exhibited higher expression of MALAT1 compared with PNT2, an immortalized nontumorigenic normal prostate epithelial cell line." (PMID 37812088, 2023).
glioma (126 papers, 2013 to 2025). A benign or malignant brain and spinal cord tumor that arises from glial cells (astrocytes, oligodendrocytes, ependymal cells). "Metastasis-associated lung adenocarcinoma transcript 1 (MALAT1) is one of the cancer-promoting long non-coding RNAs that are overexpressed in human glioma tissue and positively correlated with tumor malignancy and poor patient survival." (PMID 38675144, 2024). "Recent studies have indicated that MALAT1 lncRNA has promising potential to serve as a diagnostic biomarker for gliomas and other cancers with sufficient specificity and sensitivity." (PMID 37444408, 2023). "MALAT1 was significantly downregulated in glioma samples and associated with tumor grade, tumor size and Karnofsky Performance status in glioma patients." (PMID 35928868, 2022). "LncRNA-MALAT1 has been considered as a tumor suppressor and down expression of MALAT1 to cause remarkable promotion of invasion and proliferation of the glioma cells." (PMID 33750353, 2021). "In U87MG, U118, U251, U373, and D247 glioma cells, autophagy activation and cell proliferation can be triggered by metastasis-associated lung adenocarcinoma transcript 1 (Malat1)." (PMID 34204169, 2021). "MALAT1 lncRNA has been shown to be downregulated in glioma tissue and cell lines, and high MALAT1 levels are associated with improved survival in glioma patients." (PMID 34316694, 2021). "It is also indicated that the aberrant overexpression of MALAT1 is associated with WHO glioma grade significantly (I–II vs. III–IV; P = 0.007) and with glioma size (<3 cm vs. T ≥ 3 cm; P = 0.008)." (PMID 32117213, 2019). "Loss of MALAT-1 in a glioma stem cell line is associated with loss of expression of SOX2 and Nestin, both essential stemness markers." (PMID 28430163, 2017). "Conversely, overexpression of MALAT1 caused significant reduction in cell proliferation and invasion in vitro, and tumorigenicity in both subcutaneous and intracranial human glioma xenograft models." (PMID 26938295, 2016). "Additionally, MALAT1 (metastasis-associated lung adenocarcinoma transcript 1) is implicated in glioma proliferation and migration by modulating transcription factors and splicing regulators." (PMID 40076844, 2025). "Thus, here we checked m6A modifications of previously reported glioma associated lncRNAs: MALAT1, NEAT1, XIST1, TUG1, CRNDE, LINC00461, and HOTTIP." (PMID 35361860, 2022). "Moreover, MALAT1 was associated with poor outcomes in glioma patients, and silencing of MALAT1 resulted in reduced cell proliferation and caused cycle arrest and apoptosis." (PMID 35071748, 2022). "MALAT1 is known as a prognostic indicator in non-small cell lung cancer, but is abnormally expressed in various human cancers; it is upregulated in gliomas, where its expression is associated with the progression of glioma and poor prognosis." (PMID 33980320, 2021). "lncRNA metastasis-associated lung adenocarcinoma transcript 1 could stimulate glioma metastasis through suppressing autophagy." (PMID 33613672, 2021). "An overexpression of MALAT1 is associated with suppressed of glioma cells." (PMID 30583549, 2018). "Similarly, increased expression of NEAT1, HOTAIR, and MALAT1 was also found associated with poor prognosis in glioma." (PMID 29138748, 2017). "One study showed that MALAT1 associated with the malignant status and poor prognosis in glioma." (PMID 28187000, 2017). "Recently, the Wang group demonstrated that METTL3 promoted the malignant progression of IDH-wt gliomas while upregulating the expression of the lncRNA MALAT1 by enhancing its stability via m6 A modification." (PMID 40382536, 2025). "Further, Malat1 is altered in AD patient plasma and CSF and has been found in glioma stem cell-derived extracellular vesicles." (PMID 41245137, 2025).